CDK5 (cyclin dependent kinase 5)
Diseases named in the same sentence as CDK5 in open-access papers (continued):
Sharing a sentence is not in itself a finding about the gene and the disease.
neurological disorders (32 papers, 2009 to 2025). "The p25–CDK5 complex results in a hyperactivated state of CDK5, causing widespread intracellular hyperphosphorylation and contributing to the development of neurological diseases." (PMID 40650017, 2025). "The reduction or complete inactivity of CDK5 is also harmful, which can cause neurological diseases or intellectual disorders, such as severe type 1 neurofibromatosis or schizophrenia and spontaneous attacks." (PMID 33805800, 2021). "DLGAP1 was also implicated in Alzheimer’s and other neurological disorders, where as a direct substrate of CDK5, it undergoes phosphorylation and proteasomal degradation leading to synaptic actin remodeling and ultimately to a synapse loss." (PMID 31321035, 2019). "CDK5 plays important roles in neural development and function, and dysfunction of CDK5 is associated with a number of neurological disorders." (PMID 30618612, 2018). "In particular, calpain-specific cleavage of Cdk5-p35 to p25 has been implicated in the neurological damage seen in many neurological disorders." (PMID 29209207, 2017). "Fast decompression affected several proteins taking parts in these two main mechanisms of synaptic strength, as alteration in CDK5/calcineurin shown by others, to be associated with a broad range of neurological disorders as previously reviewed." (PMID 28977037, 2017). "Cyclin-dependent kinase 5 (Cdk5) is a proline-directed serine/threonine kinase that has been implicated in learning, synaptic plasticity, neurotransmission, and numerous neurological disorders." (PMID 19529798, 2009). "The combination of p25 and CDK5 will cause CDK5 to be in an over-activated state, thereby hyperphosphorylating various substrates in cells, causing abnormal pathophysiological responses, and leading to neurological diseases." (PMID 35966199, 2022). "Future extensive studies are still needed to define more precisely the role of Cdk5 hyperactivation in brain function impairments, and it will facilitate the discovery of more effective therapeutic strategies targeting Cdk5 aberrant activity implicated in neurological disorders." (PMID 36438186, 2022). "Thus, the hyperactivation and mislocalization of Cdk5 caused by p25 accumulation lead to the dysfunction of Cdk5, which contributes to the pathogenesis of various neurological diseases." (PMID 36438186, 2022). "In addition, fast decompression affected several proteins taking parts in these two main mechanisms of synaptic strength, especially alteration in CDK5/calcineurin are associated with a broad range of neurological disorders." (PMID 28977037, 2017). "Due to the many roles of CDK5 in the development of the nervous system, as well as the effects of cellular stress on CDK5 activation, CDK5 has been implicated in the progression of various neurological diseases and as a potential therapeutic target in disease treatment." (PMID 28077789, 2017). "Numerous Cdk5 inhibitors have been reported to mitigate neurological disorders in mouse models, and some small peptides have been shown to inhibit the Cdk5–p25 complex, thereby protecting against neurodegeneration." (PMID 41154594, 2025). "Partial knockdown of Cdk5 or inhibition of Cdk5 activity is considered a therapeutic strategy to rescue neurological disorders." (PMID 40224020, 2025). "Reduced activity and hyperactivity of Cdk5 are equally neurotoxic, leading to various neurological disorders." (PMID 41154594, 2025). "Therefore, it is essential to establish the causality in the association between CDK5 signaling and cholinergic neuronal activity; hence, an approach will provide a viable rescue strategy to reverse the cellular adaptations and behavioral symptoms of neurological disorders." (PMID 37223477, 2023). "Summary of the main targets of cdk5 in neurological diseases and mechanism of Cdk5 and nervous system diseases." (PMID 35966199, 2022).
neurological disorders (continued). "Cdk5 inhibitors have shown promising effects in numerous studies and Cdk5 has great potential as a therapeutic target for neurological disorders." (PMID 35966199, 2022). "In general, our understanding of Cdk5 in neurological disorders has made great progress in recent years." (PMID 35966199, 2022). "Aberrant activation of Cdk5 appears to be a driving force for the initiation and progression of multiple neurological disorders." (PMID 36438186, 2022). "It is increasingly clear and certain that Cdk5 plays a pivotal role in the physiological function of the nervous system and the pathological process of neurological disorders." (PMID 35966199, 2022). "In this review, we will summarize recent advances in the molecular mechanisms of Cdk5 in neurological diseases as well as the therapeutic potential of Cdk5 in these neurological diseases." (PMID 35966199, 2022). "Numerous Cdk5 substrates have been detected and their abnormal alterations following aberrant Cdk5 activity are closely related with initiation and progression of neurological disorders." (PMID 36438186, 2022). "The binding to truncated co-activators results in aberrant Cdk5 activity and contributes to the initiation and progression of multiple neurological disorders through affecting the down-stream targets." (PMID 36438186, 2022). "Epigenetic editing of Cdk5 also has been applied to neurological disorders, such as sex-specific regulation of fear memory." (PMID 35966199, 2022). "The extensive actions of Cdk5 discussed in this review suggest that it is a promising therapeutic target for neurological diseases." (PMID 36438186, 2022). "Together, CIP/TFP5 and Cdk5i offer an exciting approach to attenuate aberrant Cdk5 activity observed in a number of neurological disorders and thereby alleviate pathologies and improve cognitive functions." (PMID 34814918, 2021). "Due to the fact that CDK5 plays important roles during the development of the nervous system; therefore, any disruption of CDK5 activation can lead to many neurological diseases." (PMID 33805800, 2021). "Taken together, our findings reveal that Cdk5/p35 regulates spatial learning and memory, implicating Cdk5/p35 as a therapeutic target in neurological disorders." (PMID 25404232, 2014). "These influence many neurological disorders, but the very breadth of Cdk5 effects has made it difficult to synthesize a coherent picture of the part played by this protein in health and disease." (PMID 25364642, 2012). "The use of CDK5 inhibitors in both in vitro and in vivo studies has demonstrated neuroprotective effects, suggesting that CDK5 may serve as a potential therapeutic target for neurological diseases in the future." (PMID 40650017, 2025). "List of major Cdk5 substrates reviewed in neurological disorders." (PMID 36438186, 2022). "Whether there are any other acetylation sites remains unclear, and the role of Cdk5 acetylation in neurological diseases is also still needed to be further investigated." (PMID 36438186, 2022). "Therefore, we comprehensively summarized the role of Cdk5 in a series of common neurological disorders in this paper." (PMID 36438186, 2022). "Cdk5 plays an important role in the pathological process of neurological diseases." (PMID 35966199, 2022). "The aberrant Cdk5 activity is critically involved in the pathogenesis of neurological disorders, so the regulation of kinase activity may be a potential strategy for disease treatment." (PMID 36438186, 2022). "However, many issues, such as the more detailed molecular mechanisms of Cdk5 in different neurological disorders and the development of more selective inhibitors of CDK5, still need to be further clarified before its clinical application." (PMID 35966199, 2022). "However, roscovitine can also inhibit Cdk1, Cdk2, Cdk7, and Cdk9, the low selectivity for Cdk5 reduces its potential as a drug candidate targeting neurological disorders." (PMID 36438186, 2022).
neurological disorders (continued). "Given the broad spectrum of CDK5 action in neurons under physiological and pathological conditions, our findings lay the foundation to further understand brain development and the etiology of neurological disorders." (PMID 30209341, 2018). "Given the many ways in which Cdk5 modulates neural structure and activity, it is not surprising that alterations of Cdk5 activity are associated with an equally broad range of neurological disorders." (PMID 25364642, 2012). "But it may shed light upon the treatment of Cdk5-related neurological diseases." (PMID 36438186, 2022). "The role of Cdk5 in nervous system diseases may be different in male and female models." (PMID 35966199, 2022). "Therefore, in this review, we will briefly introduce the physiological and pathological mechanisms of Cdk5 in the nervous system, focusing on the recent advances of Cdk5 in neurological disorders and the prospect of targeted Cdk5 for the treatment of neurological disorders." (PMID 35966199, 2022). "Interestingly, synergistic neuroprotective effect of Cdk1 and Cdk5 inhibition may be extended to other neuropathological conditions, as both enzymes are individually recognized to contribute to cell death in several neurologic diseases." (PMID 29581894, 2018). "In the final section of this review we will consider how disruptions in the function of Cdk5, and particularly those functions related to neuronal excitability, neurotransmission, protein trafficking and the compartmentalization of the neuron, contribute to neurological disease." (PMID 25364642, 2012). "A successful Cdk5 inhibitor for neurological diseases should be able to pass the BBB and have a high Cdk5 selectivity." (PMID 36438186, 2022). "Preclinical studies demonstrated that administration of Cdk5 inhibitors improve neurological disorders in mice, though none of these inhibitors has proven effectual in clinical trials." (PMID 38842132, 2024). "We focused on CDK5 and CDK1 because these two CDKs, unlike other CDKs, are involved in neurological disorders." (PMID 39596381, 2024).
infection (15 papers, 2009 to 2024). The state of being infected such as from the introduction of a foreign agent such as serum, vaccine, antigenic substance or organism. "As upstream signalling molecules of IFN-β production, TBK1, IRF3 and P65 displayed higher phosphorylation in CDK5 knockdown cells after infection with VSV." (PMID 37332205, 2023). "In neutrophils, CDK5 can regulate the secretion of cytokines during infection or injury by phosphorylating vimentin." (PMID 37332205, 2023). "Infection of cultured hippocampal neurons with CDK5-kd2 resulted in a strong reduction of mAb7a-immunoreactive puncta." (PMID 25093719, 2014). "Although the upregulation of TrkB after CFA infection was decreased by administration of roscovitine, this data was not sufficient to confirm the close and direct interaction between Cdk5 and TrkB." (PMID 24465591, 2014). "Consistent with our previous findings, expression of both GABRA6 and CDK5 was decreased following infection with MCMV when compared to control mice." (PMID 23505367, 2013). "For this purpose, differentiating NPCs were pre-treated with Roscovitine, or transfected with siRNA targeting CDK5 for 6 hrs, followed by infection with adenovirus expressing p35." (PMID 21943307, 2011). "In addition, CDK5 was shown to regulate secretion of cytokines by neutrophils in response to injury or infection." (PMID 31910742, 2020). "To directly test whether Cdk5 is responsible for CFA-induced behavioural impairments, we measured the PWL and tested the EPM and OFT after a contralateral or an ipsilateral Cdk5 shRNA infection." (PMID 26179626, 2015). "The same results were detected in co-infection of dominant negative Cdk5 (DNCdk5) with p25." (PMID 24039692, 2013). "Based on those previous results, the strong inhibition of CDK5 signaling at 20 h of IMI seems to indicate a degree of modulation or control of pain through decrease nociception within mammary tissue prior peak clinical signs of infection." (PMID 19925655, 2009). "Genes involved in cell cycle CDK4, CDK5, Cyclin E1, CKN2B, CDKN2D were down-regulated at all time-points post infection." (PMID 20828378, 2010). "QRT-PCR analysis revealed that at early stage of infection (day 1 p.i.), mRNA levels of cell cycle genes such as CDC2, CDC25A, Cyclin E, CDK5, CDK8 and Cyclin G1 were significantly (P<0.05) upregulated in A. phagocytophilum-infected cells in comparison to uninfected controls." (PMID 28797056, 2017). "Given that APP is substrate for several kinases including GSK-3, JNK and Cdk-5, we studied their involvement in HSV-1-induced APP phosphorylation by adding specific kinase inhibitors to the culture medium of infected cells during the entire post-infection (p.i.)time." (PMID 26487282, 2015). "We investigated the impact of the MAPK family inhibitors Selumetinib (MEK1 and MEK2) and JNK-IN-8 (JNK family), and the impact of CDK family kinase inhibitors Roscovitine (CDK2, CDK5), Dinaciclib (CDK4, CDK6), and the non-specific CDK/Crk during infection (Fig. EV2A,B)." (PMID 38177504, 2024).
neurodevelopmental disorder (6 papers, 2017 to 2025). A behavioral and cognitive disorder with onset during the developmental period that involves impaired or aberrant development of intellectual, motor, or social functions. "This study is the first to reveal that CDK5 mediates BPD‐associated neurodevelopmental disorders in premature infants." (PMID 36964998, 2023). "This study first found a vital role of CDK5 in BPD‐associated neurodevelopmental disorders." (PMID 36964998, 2023). "Although we proposed a new mechanism between lung injury and neurodevelopmental disorders in infants with BPD, more work is needed to elucidate the role of CDK5 in different brain regions in the regulation of BPD brain injury and to uncover the mechanisms involved." (PMID 36964998, 2023).
psychiatric disorder (5 papers, 2014 to 2025). A disorder characterized by behavioral and/or psychological abnormalities, often accompanied by physical symptoms. "Several reports have implicated the involvement of CDK5 and other components of the UFMylation system in neuronal development and multiple psychiatric disorders." (PMID 40188151, 2025). "It has been proposed that CDK5 modulates the brain reward system and that it is consequently linked to psychiatric diseases." (PMID 31687929, 2019). "Because PER2 is involved in several physiologically relevant pathways in addition to clock regulation, PER2 may mediate several biological functions that were previously linked to CDK5, such as the regulation of the brain reward system and psychiatric diseases." (PMID 31687929, 2019). "More and more evidences have shown that Cdk5 dysfunction plays important roles in psychiatric disorders." (PMID 36438186, 2022).
brain disorder (3 papers, 2021 to 2024). A disease affecting the brain or part of the brain. "Cyclin-dependent kinase 5 (Cdk5) is a promising kinase that has been implicated in various brain disorders, including TBI." (PMID 38200156, 2024). "Impaired CDK5 loses its original functions such as plastic synapse, cytoskeletal polypeptides phosphorylation, alive neurons, and developmental neurons, directly contributing to multiple brain disorders and interrupted communication between pivotal organelles." (PMID 34681938, 2021). "Therefore, whether the modulation of Cdk5 on PV excitability is involved in the pathogenesis of these brain disorders is worthy to be investigated." (PMID 35008611, 2021).
metabolic disease (3 papers, 2016 to 2025). A congenital disorder (due to inherited enzyme abnormality) or acquired (due to failure of a metabolically important organ) disorder resulting from an abnormal metabolic process. "The modulation of neurodegenerative markers, including NF-H, NF-L, and tau phosphorylation, highlights the potential of CDK5 inhibitors as promising therapeutic interventions for neurodegenerative conditions associated with metabolic disorders." (PMID 40224020, 2025). "In addition, CDK5 plays a role in the pathogenesis of various metabolic diseases." (PMID 32054125, 2020).
central nervous system disorder (2 papers, 2019 to 2025). A disease involving the central nervous system. "In particular, CDK5 activity during oxidative stress has been found to contribute to the pathophysiology of various central nervous system disorders." (PMID 31644666, 2019). "We found that the 5-HT7 receptor-mediated reversal of mGluR-LTD also involved activation of cyclin-dependent kinase 5 (Cdk5), a kinase that plays a physiological role in brain development and function and is disrupted in several disorders of the central nervous system." (PMID 40141138, 2025).
heart disease (2 papers, 2021 to 2024). "We speculate that manipulation of CDK5 activity has therapeutic potential for heart disease." (PMID 34379189, 2021).
hematologic malignancies (2 papers, 2021 to 2022). "We evaluated fadraciclib, a CDK2/CDK5/CDK9 inhibitor which has successfully completed a First-in-Human Phase I clinical trial, and is continuing clinical development in both solid tumors and hematological malignancies." (PMID 34465787, 2021).
autosomal dominant disease (1 paper, 2025). Autosomal dominant form of disease. "Decades of research indicate that calcium dysregulation is an early driver of AD pathology in both sporadic and autosomal dominant disease, with elevated calcium in the cytosol, rather than stored in the SER, activating calpain-2 to disinhibit GSK3β and cdk5 to hyperphosphorylate tau." (PMID 40365352, 2025).
cardiovascular diseases (1 paper, 2022). "In recent years, abnormal CDK5 expression is associated with some neurodegenerative or cardiovascular diseases." (PMID 35795154, 2022).
movement disorder (1 paper, 2023). Neurological conditions resulting in abnormal voluntary or involuntary movement, which may impact the speed, fluency, quality and ease of movement. "A short peptide termed Myr‐C9orf72 was used to verify whether interfering with Cdk5 phosphorylation at the Ser9 site of the C9orf72 protein could alleviate autophagy disorder, neuronal death, and movement disorder in PD models." (PMID 37353944, 2023).
peripheral neuropathy (1 paper, 2025). A disorder affecting the peripheral nervous system. "Therefore, it is conceivable that off-target inhibition of neuronal CDK5 (or other related kinases) by CDK4/6 inhibitors could disrupt normal neuronal function and contribute to the development of peripheral neuropathy in a subset of patients." (PMID 41458615, 2025).
CDK5 also shares sentences with these, for which no sentence is quoted: Parkinson’s (8 papers); acute myeloid leukemia (3); nasopharyngeal carcinoma (3); small cell lung carcinoma (3); adenocarcinoma (2); axonal neuropathy (2); benign neoplasm (2); brain cancer (2); clear cell Renal Cell Carcinoma (2); cocaine abuse (2); head and neck cancer (2); hyperhomocysteinemia (2); squamous cell carcinoma (2); systemic sclerosis (2); anaplastic thyroid cancer (1); anxiety disorder (1); astrocytic tumor (1); attention deficit-hyperactivity disorder (1); autism spectrum disorder (1); B-cell lymphoma (1); blood cancers (1); brain malformation (1); Burkitt lymphoma (1); carcinoma in situ (1); cerebrovascular diseases (1); chronic cervicitis (1); chronic kidney disease (1); chronic myelocytic leukemia (1); cocaine use disorder (1); cognitive (1).
A further 55 diseases each share a sentence with CDK5 in 1 paper.